TBK1 (TANK binding kinase 1)
Diseases named in the same sentence as TBK1 in open-access papers (continued):
Sharing a sentence is not in itself a finding about the gene and the disease.
liver fibrosis (8 papers, 2020 to 2026). "The analysis demonstrated that increased TBK1 expression was associated with higher degree of platelet-to-albumin ratio, liver fibrosis and tumor stage." (PMID 33679751, 2021). "Evidences reveal that STING and TBK1 expression in monocyte-derived macrophages is closed related to the development of liver fibrosis in patients with nonalcoholic fatty liver disease." (PMID 35924048, 2022). "Owing to the correlation of TBK1 expression with inflammation indicators (liver fibrosis, platelet-to-albumin ratio), the present study investigated the effects of TBK1 expression on HCC immune infiltration." (PMID 33679751, 2021). "Collectively, we found that inhibition of the TBK1 and IKKε by amlexanox is a promising therapeutic strategy to cure liver fibrosis." (PMID 31821710, 2020). "To further explore the role of TBK1 and IKKε in fibrotic responses, we next performed additional experiments using hepatotoxin‐induced liver fibrosis model." (PMID 31821710, 2020). "Contrary to not clearly understood role of TBK1 and IKKε on liver fibrosis, the role of canonical IKKα and IKKβ were broadly understood in the progression or resolution of liver fibrosis." (PMID 31821710, 2020). "Inhibition of TBK1 by amlexanox protects against liver fibrosis induced by CCl4." (PMID 35924048, 2022). "Furthermore, consistent with the other study, our results showed the suppression of the activation of hepatic stellate cells and liver fibrosis by TBK1 antagonist." (PMID 33679751, 2021). "In addition, TBK1 inhibition has a significant anti-fibrotic role in pulmonary and liver fibrosis." (PMID 35924048, 2022). "Moreover, patients with a more advanced T classification (P = 0.020), severer vascular invasion (P = 0.031), higher degree of liver fibrosis (P = 0.017), and higher value of platelet-to-albumin ratio (P = 0.027) tended to have higher mRNA expression levels of TBK1." (PMID 33679751, 2021). "Although numerous studies have suggested that canonical IκB kinases (IKK) play a key role in the progression of liver fibrosis, the role of non‐canonical IKKε and TANK‐binding kinase 1 (TBK1) on the development and progression of liver fibrosis remains unclear." (PMID 31821710, 2020). "As more effective therapeutic strategies are urgently needed for treating hepatic fibrosis and cirrhosis, inhibition of TBK1 and IKKε by amlexanox may be a promising therapeutic strategy to cure fibrosis, which could allow for remodelling and regression of fibrosis." (PMID 31821710, 2020). "Therapeutic restoration of TBK1 expression via AAV8 delivery in MASH mouse model enhanced mitophagy, reduced mitochondrial burden and ameliorated liver fibrosis." (PMID 41826645, 2026). "Therapeutic restoration of TBK1 expression via AAV8 delivery enhanced mitophagy, reduced mitochondrial burden, and ameliorated liver fibrosis." (PMID 41282122, 2025). "Furthermore, when WT mouse hepatocytes were treated with ccl4, ER stress activated the STING signaling pathway, resulting in extensive phosphorylation of TBK1 and IRF3, increased hepatocyte apoptosis, and liver fibrosis." (PMID 38525112, 2024). "Interestingly, inhibition of TBK1 in mouse liver by the TBK1 inhibitor BX795 reduces p62 inclusions, production of ROS, and liver fibrosis during NASH." (PMID 33976943, 2021). "We analyzed the TBK1 expression based on eight widely recognized clinicopathological parameters of the HCC data set from TCGA, including age, gender, alpha-fetoprotein (AFP), tumor stage, tumor grade, T classification, vascular invasion, liver fibrosis, and the value of platelet-to-albumin ratio." (PMID 33679751, 2021).
Cognitive impairment (7 papers, 2019 to 2024). Abnormal cognition is characterized by deficits in thinking, reasoning, or remembering. "The reported clinical features of ALS associated with TBK1 mutations are variable in the age of onset, progression of the disease, survival duration, and presence of cognitive impairment and extrapyramidal symptoms." (PMID 35283724, 2022). "Interestingly, about half of the patients with TBK1 mutations were identified with cognitive impairment and one‐thirds with bulbar symptoms." (PMID 30672142, 2019). "Esketamine has been shown to reduce cognitive impairment by stimulating the activity of the interferon GRNES/TANK-binding kinase 1(TBK1) signaling pathway." (PMID 38302944, 2024). "The ALS patients carrying TBK1 intronic mutations in the study showed typical clinical features of ALS without cognitive impairment." (PMID 35283724, 2022). "The TBK1 p.Ile334Thr mutation was first reported in a sporadic ALS (sALS) patient without cognitive impairment." (PMID 30672142, 2019). "No cognitive deficits were found in patients carrying variants in other genes, with the exception of three mutated patients in TARDPB (c.883G > A p.Gly295Ser), TBK1 (c.225G > C p.Glu75Asp), and CHCHD10 (c.100C > T p.Pro34Ser), respectively." (PMID 33770234, 2021).
motor neuron disease (7 papers, 2017 to 2025). "For example, mice carrying the human TBK1 p.E696K variant that specifically abrogates optineurin binding developed autophagolysosomal defects, which precipitated the age-associated motor neuron disease." (PMID 41226491, 2025). "With regard to the TBK1 genotype-phenotype relationship, more than half of patients with LoF variants were clinically diagnosed with pure motor neuron disease (MND), which mainly comprised ALS, rare cases with progressive bulbar palsy." (PMID 30534373, 2018). "TBK1 p.N22H, p.R228H, and p.E476fs were previously reported in ALS, ALS, and motor neuron disease, respectively." (PMID 40813364, 2025). "Similarly, genes such as TANK-binding kinase-1 (TBK1), Sequestosome-1 or p62 (SQTSM1), Optineurine protein (OPTN), and Valosin-containing protein (VCP) that are associated with FTD, inclusion body myositis, motor neuron disease, and Paget's disease encode proteins related to protein degradation." (PMID 35115992, 2021). "FTLD-TDP cases without motor neuron disease have been reported in association with OPTN and TBK1 (Tank-binding kinase mutations." (PMID 34093394, 2021). "Interestingly, however, deletion of Tbk1 in SOD1G93A transgenic mice (a typical model of motor neuron disease/ALS), did not affect symptoms onset nor survival." (PMID 31039129, 2019).
non-alcoholic fatty liver disease (7 papers, 2019 to 2025). "Studies have confirmed that myeloid-specific TBK1 deficiency promotes M1 macrophage polarization in the adipose and liver tissues of non-alcoholic fatty liver disease (NAFLD) mice, promoting adipose tissue inflammation and hepatitis." (PMID 40076567, 2025). "Recent clinical studies have also shown that IKKε/TBK1 inhibitor can improve hepatic steatosis and insulin sensitivity in obese patients with non-alcoholic fatty liver disease (NAFLD) and T2D17." (PMID 35962183, 2022). "Finally, attempts were made to correlate the observed regulation of TBK1 expression and activity by BRG1 to a functional readout relevant in the pathogenesis of non-alcoholic fatty liver disease." (PMID 34660604, 2021).
non-small cell lung carcinoma (7 papers, 2015 to 2025). A group of at least three distinct histological types of lung cancer, including non-small cell squamous cell carcinoma, adenocarcinoma, and large cell carcinoma. "TBK1 induces anti-apoptosis in KRAS-mutated non-small cell lung cancer cell lines by activating NF-κB, and the TBK1-mediated pathway has been further investigated in various other KRAS-mutated tumors." (PMID 39161768, 2024). "Clinical studies have identified high expression levels of TBK1 in the tumor tissues of stage 1 non-small cell lung cancer (NSCLC) patients that were significantly correlated with poor prognosis." (PMID 40076567, 2025). "Studies have demonstrated that TBK1-IFN signaling can be enhanced by pemetrexed to improve the immunogenicity of EGFR-TKI resistant non-small cell lung cancer (NSCLC) cells with MET amplification." (PMID 39161768, 2024). "Dong and colleagues reported that cilengitide reversed erlotinib resistance by inhibiting the Galectin-3/KRAS/RALB/TBK1/NF-κB signaling pathway in non-small cell lung cancer." (PMID 35142593, 2022). "Of note is that TBK1 is also a critical component of enhanced autophagy and NF-κB activation in K-Ras-dependent non-small cell lung carcinoma (NSCLC)." (PMID 31131275, 2019). "TBK1 is essential for the survival of non-small cell lung cancers driven by oncogenic KRAS9, 10, 11; this synthetic lethal interaction of TBK1 with mutant K-Ras was governed by its ability to activate NFκB anti-apoptotic signalling through c-Rel and BCL-XL." (PMID 26656453, 2015). "In a non-small cell lung cancer (NSCLC) study, a subset of cancer cells exhibited sensitivity to TBK1 inhibition, which was correlated with activation of Akt and mTORC1 (mechanistic target of rapamycin complex 1) signaling." (PMID 30223576, 2018). "For instance, TBK1 phosphorylates AGO2, which functions with double-stranded miRNA, to generate carcinogenic miRISC via the S417 site, a process related to the resistance of gefitinib targeted therapy in non-small cell lung cancer." (PMID 39161768, 2024).
ZIKV infection (7 papers, 2018 to 2025). "ZIKV infection of RGCs caused centrosomal depletion and mitochondrial sequestration of phospho-TANK-binding kinase 1 (TBK1), resulting in abnormal mitoses, architectural disorganization and cell death." (PMID 35371036, 2022). "This study showed that ZIKV infection causes mitochondrial apoptosis in neuronal stem cells via mitochondrial sequestration of phospho-TBK1 during mitosis." (PMID 31882804, 2019). "In human neuroepithelial stem cells, ZIKV infection disrupts the localization and activity of TBK1 by sequestering the phosphorylated TBK1 to the mitochondria during mitosis." (PMID 36831177, 2023). "The functions of several mitosis-associated proteins, CEP152 and pericentrin (centrosomal), CENPJ (centromere) and TBK1 kinase (centrosomal) are affected during ZIKV infection, leading to mitotic defects and premature differentiation or cell death." (PMID 35412344, 2022). "We have recently reported that ZIKV infection occurs through the involvement of the TBK1 protein and its active form phospho-TBK1 (pTBK1)." (PMID 32806773, 2020). "This suggests that TBK1 is one of the major targets of ZIKV infection." (PMID 30374352, 2018). "ZIKV infection disrupts TBK1 relocation from the centrosome to the mitochondria which may lead to impaired mitosis and cell division." (PMID 30374352, 2018). "In this study, TRIM38 overexpression in U251 cells increased the expression of RIG-I/MDA5 signaling pathway-related proteins, including RIG-I, MDA5, TBK1, and IRF3, at 6 h post-ZIKV infection, and also increased the IFN-β level." (PMID 40006954, 2025).
atherosclerosis (6 papers, 2022 to 2025). A disease characterized by the build-up of fatty material and calcium deposition in the arterial wall resulting in partial or complete occlusion of the arterial lumen. "Recent research has shown enhanced expression of GSDMD in atherosclerosis, where it can mediate the cGAS/STING/TBK1/IRF3/NF-κB signaling pathway, contributing to the process of atherosclerosis." (PMID 39301029, 2024).
heart failure (6 papers, 2016 to 2024). Inability of the heart to pump blood at an adequate rate to meet tissue metabolic requirements. "Ginsenoside Rd increases reticulin secretion in adipose tissue via TBK1-AMPK and enhances mitochondrial biogenesis in heart failure through the Wnt5a/Ca2+ pathway." (PMID 39141645, 2024).
HIV-1 infection (6 papers, 2017 to 2025). The type species of lentivirus and the etiologic agent of acquired immunodeficiency syndrome (AIDS). "In line with this possibility, recent studies suggest that mDCs treated with adjuvants targeting TBK1 are associated with reduced depletion of CD4+ T cells and polyfunctional HIV-1 specific CD8+ T cells in humanized mice after HIV-1 infection." (PMID 36569826, 2022). "The mitochondrial antiviral protein MAVS signals downstream of MDA5 and DDX3, serving as a platform for TBK1/IKKE activation, and is therefore able to elicit the antiviral type I IFN and cytokine responses needed to combat HIV-1 infection." (PMID 39665545, 2025).
Hyperglycemia (6 papers, 2023 to 2025). An increased concentration of glucose in the blood. "Cos treatment markedly suppressed hyperglycaemia‐induced IκB‐α degradation and inhibited the phosphorylation of TBK1 and P65, indicating the anti‐inflammatory effect of Cos in diabetic hearts." (PMID 36810875, 2023). "The TBK1 inhibitor reverses hyperglycemia-induced HIF-1α expression." (PMID 38674050, 2024). "Hyperglycemia may aggravate the complexity of coronary atherosclerosis by activation of TBK1–HIF-1α-mediated IL-17/IL-10 signaling in macrophages." (PMID 38674050, 2024).
influenza (6 papers, 2013 to 2022). An acute viral infection of the respiratory tract, occurring in isolated cases, in epidemics, or in pandemics; it is caused by serologically different strains of viruses (influenzaviruses) designated A, B, and C, has a 3-day incubation period, and usually lasts for 3 to 10 days. "While it is clear that both VSV and influenza infections can involve TLR4, the cytosolic nucleic acid innate immune receptors play a large role in detecting RNA viruses and initiating an IFN response via the TBK-1/IRF3 axis." (PMID 23853595, 2013).
kidney cancer (6 papers, 2020 to 2025). Primary or metastatic malignant neoplasm involving the kidney. "We recently identified TBK1 as a synthetic lethal target in VHL-deficient kidney cancer, and inhibitors of TBK1 such as BX795, CYT387 481 (momelotinib), and MRT67307 can boost the efficacy of immune checkpoint inhibitors." (PMID 33808542, 2021). "TBK1 contributes to kidney cancer cell growth by phosphorylating p62/SQSTM1 on Ser366, thus stabilizing p62." (PMID 33142830, 2020). "In kidney cancer, under normoxia, PPM1B binds to TANK-binding kinase 1 (TBK1) and decreases its activity, whereas under hypoxia, PPM1B cannot dephosphorylate TBK1." (PMID 39776803, 2025).
lung adenocarcinoma (6 papers, 2021 to 2024). A carcinoma that arises from the lung and is characterized by the presence of malignant glandular epithelial cells. "Interestingly, we found an inverse correlation between the expression of IKKi and TBK1 with patient prognosis in lung adenocarcinomas." (PMID 37036972, 2023). "It has been reported that activation of TBK1 and STAT1 played important roles in IFN-γ sensitivity in lung adenocarcinoma." (PMID 38625657, 2024).
cholangiocarcinoma (5 papers, 2021 to 2024). A carcinoma that arises from the intrahepatic biliary tree (intrahepatic cholangiocarcinoma) or from the junction, or adjacent to the junction, of the right and left hepatic ducts (hilar cholangiocarcinoma). "The results indicate a significant upregulation of IKKε (encoding gene IKBKE) and TBK1 expression but a decrease in IRF3 expression within the intrahepatic cholangiocarcinoma metastasis group." (PMID 38817870, 2024). "And we observed significant positive correlations between the expression levels of DDX58, C6orf150, TMEM173, IKBKE, and TBK1, and the infiltration levels of macrophages in cholangiocarcinoma." (PMID 38817870, 2024). "Recently, it was reported that chitinase 3-like 1 (Chi3l1) binds to CD44 and induces the phosphorylation of β-catenin at Ser552 by Akt in glioblastomas and TANK-binding kinase 1 (TBK1) in cholangiocarcinomas, leading to its nuclear translocation." (PMID 38136210, 2023). "Furthermore, studies have demonstrated that the serine/threonine kinase TBK1 can promote cholangiocarcinoma progression by directly regulating β-catenin phosphorylation." (PMID 38817870, 2024). "To gain a deeper understanding of the relevance and underlying mechanisms of the innate immune pathway in cholangiocarcinoma, we investigated the expression levels of DDX58, MAVS, C6orf150, TMEM173, IKBKE, TBK1, and IRF3 in different cell types using the TISCH2 database." (PMID 38817870, 2024). "The results further suggested that Cho-TBK1-HDO may be a novel nucleic acid therapeutic for cholangiocarcinoma." (PMID 36928362, 2023). "In the present study, we found that TBK1 is highly expressed mainly in mesenchymal phenotype cholangiocarcinoma tissues, and exerts a critical role in maintaining the tumor-promoting function indicating that TBK1 is also a potential therapeutic target for CCA." (PMID 36928362, 2023). "Tissue samples from the HPA database were analyzed to determine the functions of DDX58, MAVS, C6orf150, TMEM173, IKBKE, TBK1, and IRF3 in cholangiocarcinoma cells." (PMID 38817870, 2024). "Moreover, correlation analyses showed that the expression of TBK1 correlated with the expression of E-cadherin (r = −0.3799, P < 0.001) and vimentin (r = 0.3818, P < 0.001), suggesting that TBK1 is highly expressed mainly in mesenchymal phenotype cholangiocarcinoma tissues." (PMID 36928362, 2023).
glioblastoma (5 papers, 2020 to 2025). The most malignant astrocytic tumor (WHO grade IV). "In glioblastoma stem cells (GSCs), TBK1 suppresses the core pluripotency circuitry." (PMID 39001398, 2024). "Meanwhile, in glioblastoma, HIF-1α can increase periostin (POSTN) transcription, promote TANK-binding kinase 1 (TBK1) phosphorylation in ECs, and enhance EC migration and tube formation." (PMID 40821116, 2025).
leukemia (5 papers, 2021 to 2023). A malignant (clonal) hematologic disorder, involving hematopoietic stem cells and characterized by the presence of primitive or atypical myeloid or lymphoid cells in the bone marrow and the blood. "Although TBK1 mutations have not been reported in human cancers, aberrant TBK1 activation has been implicated in the oncogenesis of several types of cancer, including leukemia and solid tumors with KRAS-activating mutations." (PMID 35395857, 2022). "It has been demonstrated that MSA-2 can activate mouse and human STING genes, induce the phosphorylation of TBK1 and IRF-3 and activate the STING signal pathway in the human leukemia monocytic cell line (THP-1 cells) and induce the expression of IFN-β, IL-1β and TNF-α via the action of TBK1." (PMID 38005816, 2023).
pancreatitis (5 papers, 2019 to 2025). Inflammation of the pancreas. "Wip1 aggravates CAE-induced autophagy and inflammatory injury in acinar cells by targeting STING/TBK1/IRF3 in experimental pancreatitis." (PMID 38671352, 2024). "In a mouse model of pancreatitis, autophagy repressed by deletion of Atg5 dysregulated TBK1 signaling and upregulated PD-L1." (PMID 31627272, 2019). "Furthermore, inhibition of TBK1 via amlexanox treatment markedly increases serum levels of infectious extracellular vesicles (EV) and severity of pancreatitis in CVB-infected mice." (PMID 40396014, 2022).